SNORD116-25 (small nucleolar RNA, C/D box 116-25)
Synonyms: HBII-85-25
Gene: Small nucleolar RNA gene on chromosome 15 (25,097,663 to 25,097,754, forward strand). Ensembl gene ENSG00000252326.
Gene Ontology:
Biological process: RNA processing
Cellular component: nucleolus
Homologues: Orthologues: chimpanzee SNORD116 (100% identical), macaque SNORD116 (99% identical), rabbit SNORD116 (73% identical), mouse Gm22373 (59% identical), rat LOC120100337 (48% identical). Paralogues in human: SNORD116-26 (95% identical), SNORD116-27 (89% identical), SNORD116-28 (77% identical), SNORD116-30 (77% identical), SNORD116-29 (74% identical), SNORD116-2 (71% identical), SNORD116-20 (71% identical), SNORD116-22 (71% identical), SNORD116-6 (71% identical), SNORD116-14 (70% identical), SNORD116-15 (70% identical), SNORD116-17 (70% identical), and 20 more.